PTPRCAP (protein tyrosine phosphatase receptor type C associated protein)
Synonyms: CD45-AP; LPAP
Tractability: Antibody: its Gene Ontology location is reachable by antibodies, with high confidence; UniProt predicts a signal peptide or a membrane-spanning region; the Human Protein Atlas places it where antibodies can reach. PROTAC: its protein half-life has been measured; a small molecule that binds it is known.
Target class: Enzyme; Protein Phosphatase; Receptor tyrosine-protein phosphatase; Tyrosine protein phosphatase; Phosphatase
Gene: Protein-coding gene on chromosome 11 (67,435,510 to 67,437,682, reverse strand). Ensembl gene ENSG00000213402.
Subcellular location: Membrane
Subcellular location (Human Protein Atlas): Plasma membrane
Gene Ontology:
Molecular function: protein binding
Biological process: defense response
Cellular component: plasma membrane; membrane
Genetic constraint (gnomAD): Loss-of-function variants: 0 observed, 1.67 expected, observed/expected ratio (o/e) 0, 90% interval 0 to 1.49. That is too few expected variants to judge how well the gene tolerates losing a copy. Missense variants: 294 observed, 245.77 expected, observed/expected ratio (o/e) 1.2, 90% interval 1.09 to 1.32. Synonymous variants: 136 observed, 122.7 expected, observed/expected ratio (o/e) 1.11, 90% interval 0.96 to 1.28.
Homologues: Orthologues: chimpanzee PTPRCAP (99% identical), macaque PTPRCAP (97% identical), pig PTPRCAP (74% identical), mouse Ptprcap (63% identical), guinea pig PTPRCAP (59% identical), rat Ptprcap (50% identical).
Diseases named in the same sentence as PTPRCAP in open-access papers:
PTPRCAP is named in the same sentence as 16 diseases in open-access papers, as found by Europe PMC text mining. Sharing a sentence is not in itself a finding about the gene and the disease. The quoted sentences say what the papers report.
gastric cancer (3 papers, 2022 to 2025). A primary or metastatic malignant neoplasm involving the stomach. "For example, changes in the expression of PTPRCAP affect the survival rate of cancer patients, and the single nucleotide polymorphism (SNP) of PTPRCAP is associated with the susceptibility of gastric cancer." (PMID 35252003, 2022). "Specifically, this allele may affect the risk of gastric cancer by increasing the expression level of PTPRCAP." (PMID 41411247, 2025). "The T allele enhances the activity of the promoter and binds to nuclear proteins, significantly increasing the expression level of PTPRCAP, which may increase the risk of gastric cancer." (PMID 41411247, 2025). "PTPRCAP is a methylation-driven key regulator related to gastric cancer." (PMID 40111834, 2025).
breast carcinoma (2 papers, 2021 to 2025). "Similar expression pattern has been observed for the PTPRCAP antibody: only 41.7% of breast carcinoma cells expressed the protein, while TILs were all positive, in all analyzed samples." (PMID 35201443, 2021).
lung carcinoma (2 papers, 2025). "The expression of PTPRCAP was significantly downregulated in lung cancer cell lines compared to the lung epithelial cell line BEAS-2B." (PMID 41411247, 2025). "Investigating the interactome of PTPRCAP in lung cancer cells will be essential to map the molecular network through which it exerts its tumor-suppressive effects." (PMID 41411247, 2025). "This further highlights the potential importance of PTPRCAP in lung cancer, but its specific role requires further investigation." (PMID 41411247, 2025). "However, at present, no research has clearly defined the specific mechanism of action of PTPRCAP in lung cancer." (PMID 41411247, 2025). "Although research on the occurrence and development of lung cancer is ongoing, the expression and role of PTPRCAP in lung cancer have not yet reached a clear conclusion." (PMID 41411247, 2025).
ovarian carcinoma (2 papers, 2022 to 2025). A malignant neoplasm originating from the surface ovarian epithelium. "Particularly in ovarian cancer with DNA repair system defects, the expression of PTPRCAP significantly increased, suggesting that PTPRCAP may play an important role in the immune response of ovarian cancer." (PMID 41411247, 2025).
autism (1 paper, 2020). Persistent deficits in social interaction and communication and interaction as well as a markedly restricted repertoire of activity and interest as well as repetitive patterns of behavior. "The protein tyrosine phosphatase receptor type C-associated protein gene (PTPRCAP) was reported to contain one of the top differentially methylated probes in autism." (PMID 32223758, 2020).
colorectal cancer (1 paper, 2021). A primary or metastatic malignant neoplasm that affects the colon or rectum.
COVID-19 (1 paper, 2023). A disease caused by infection with severe acute respiratory syndrome coronavirus 2. "T-cell activation genes PTPRCAP and CD97 were consistently upregulated in T cells from both patients with COVID-19 and HIV-1+ patients." (PMID 36992700, 2023).
lung adenocarcinoma (1 paper, 2025). A carcinoma that arises from the lung and is characterized by the presence of malignant glandular epithelial cells. "Association between PTPRCAP expression and clinicopathological characteristics of patients with lung adenocarcinoma." (PMID 41411247, 2025). "PTPRCAP (protein tyrosine phosphatase receptor C-associated protein) has been implicated in tumor suppression in several malignancies; however, its role in lung adenocarcinoma (LUAD) remains unclear." (PMID 41411247, 2025). "The results demonstrated that upregulation of PTPRCAP expression in lung adenocarcinoma A549 cells significantly inhibited the protein levels of Bcl-2 compared with the vector groups, but the expression level of BAX and Caspase-3 increased (P < 0.05, n = 3)." (PMID 41411247, 2025). "This study provides evidence that PTPRCAP acts as a potential tumor suppressor in lung adenocarcinoma (LUAD)." (PMID 41411247, 2025).
Obesity (1 paper, 2017). Accumulation of substantial excess body fat. "Moreover, the expression of FGFRL1, PNKD, PODXL, PTPRCAP, SMAD3 and WDR45L based on previously reported data correlated inversely with the methylation levels in the subcutaneous adipose tissue suggesting a potential epigenetic regulation associated to obesity." (PMID 28211912, 2017).
cancer (2 papers, 2022 to 2025). A tumor composed of atypical neoplastic, often pleomorphic cells that invade other tissues. "Recent studies have continuously revealed the role of PTPRCAP in various cancers." (PMID 41411247, 2025). "Future studies should explore whether PTPRCAP expression in LUAD influences tumor-immune interactions, but our current findings highlight a direct, cell-autonomous role in inhibiting cancer cell survival." (PMID 41411247, 2025).
tumor (2 papers, 2025). "This discovery provides a new perspective for understanding the role of PTPRCAP in tumor development." (PMID 41411247, 2025). "This shift in the balance towards apoptosis execution provides a plausible mechanism for the observed tumor-suppressive effects of PTPRCAP." (PMID 41411247, 2025). "Consistent with the in vitro results, upregulation of PTPRCAP expression significantly reduced the tumor weight (P < 0.01) and markedly decreased the tumor volume compared with the mice injected with control cells (P < 0.01)." (PMID 41411247, 2025). "In vivo xenograft experiments demonstrated that overexpression PTPRCAP inhibited tumor growth in nude mice (P < 0.001)." (PMID 41411247, 2025). "The effect of overexpression PTPRCAP on tumor growth was observed through nude mouse xenografts." (PMID 41411247, 2025). "Consistent with the mRNA findings, immunohistochemical analysis demonstrated a substantially lower positive expression rate of PTPRCAP protein in tumor tissues (22.22%, 10/45) relative to paracancerous tissues (93.33%, 42/45), with a concomitantly reduced immunoreactivity score (IRS) (P < 0.0001)." (PMID 41411247, 2025). "Additionally, PTPRCAP may also promote tumor progression through multiple mechanisms." (PMID 41411247, 2025). "PTPRCAP is downregulated in LUAD and acts as a tumor suppressor by promoting apoptosis and inhibiting proliferation, migration, and invasion." (PMID 41411247, 2025). "PTPRCAP mRNA and protein levels were significantly lower in LUAD tissues than in adjacent non-tumor tissues (P < 0.05)." (PMID 41411247, 2025).
PTPRCAP also shares sentences with these, for which no sentence is quoted: triple-negative breast carcinoma (2 papers); chordoma (1); colon cancer (1); lymph node metastasis (1); rectal cancer (1).